TXNDC5 (thioredoxin domain containing 5)
Diseases named in the same sentence as TXNDC5 in open-access papers (continued):
Sharing a sentence is not in itself a finding about the gene and the disease.
tumor (25 papers, 2014 to 2026). "In a previous study, we used custom-designed Illumina 384-SNP Vera Code microarrays to genotype 96 tag SNPs (single nucleotide polymorphisms) across the TXNDC5 locus to determine the potential association between this gene and tumor occurrence." (PMID 29207620, 2017). "The research carried out in the last few years has shown that TXNDC5 contributes to a tumor cell phenotype that can adapt to cellular stress." (PMID 38666927, 2024). "Recently, it has been shown that TXNDC5, a highly mutation-enriched region, acts as a super-enhancer that dysregulates the expression of MYC and GALM, contributing to tumor progression in MM." (PMID 38666927, 2024). "The oxidative and ER stress metabolisms are particularly often found to be downregulated in tumor cells with a high expression of TXNDC5; in consequence, TXNDC5 protects tumor cells against apoptosis." (PMID 38666927, 2024). "TXNDC5, has been seen to be expressed in lung, prostate, colon, liver, gastro, ovary, breast, and renal cell cancer and has elevated levels in tumor tissues compared to healthy counterparts." (PMID 36106447, 2022). "TXNDC5 levels were found to be elevated with increased tumor grade, tumor aggressiveness and therapy resistance." (PMID 36106447, 2022). "We further analyzed the transcription pattern of TXNDC5 in GBM samples based on tumor anatomic structure." (PMID 36106447, 2022). "For example, circRNA 104718 promotes HCC cell proliferation, migration, invasion, and tumor growth and inhibits apoptosis through the regulation of thioredoxin domain-containing protein 5 (TXNDC5) by sponging miRNA 218-5p." (PMID 35281015, 2022). "We also found evidence that ECM (extracellular matrix) production/organization is a likely mechanism for TXNDC5‐driven tumor propagation." (PMID 36106447, 2022). "The involvement of TXNDC5 in pivotal tumor‐promoting pathways also prompted us to investigate its prognostic role in GBM." (PMID 36106447, 2022). "Among the TXNDC protein family, TXNDC5 has been studied the most and was found to be overexpressed in tumor tissues, and its high expression correlates with poor survival." (PMID 33228209, 2020). "Our results are the first to show a mechanistic relationship between an ion channel-related protein and TXNDC5 and show that HERG1 exerts its effect on tumor progression by regulation of the oncogene TXNDC5 expression." (PMID 31331361, 2019). "Studies also reported that TXNDC5 expression is positively related to tumor cell differentiation, tumor cell invasion and poor survival of patients with certain tumor types." (PMID 29207620, 2017). "Studies have reported that TXNDC5 expression is increased in some tumor tissues and that its increased expression can predict a poor prognosis." (PMID 29207620, 2017). "Lymph node metastasis and the depth of tumor invasion were significantly increased in specimens that exhibited high TXNDC5 expression compared with specimens with low TXNDC5 expression." (PMID 29207620, 2017). "TXNDC5 expression was also detected in 11 (68.7%) of 16 tumor-adjacent normal tissue samples with chronic inflammation and 2 (25%) of 8 tumor-adjacent normal tissue samples without inflammation." (PMID 29207620, 2017). "A portion of mesenchymal cells in close proximity to the tumor cells exhibited very strong TXNDC5 immunoreactivity." (PMID 29207620, 2017). "Previous studies as well as our study support the notion that hypoxia-induced up-regulation of TXNDC5 not only protects endothelial cells from hypoxia-induced cell death as previously reported but also stimulates angiogenesis in tumor tissues." (PMID 29207620, 2017). "An increasing number of studies have revealed that the upregulation of TXNDC5 is found in tumors of the cervix, uterus and lungs." (PMID 25663872, 2015). "Lymph node metastasis and the depth of tumor invasion in the specimens exhibiting high TXNDC5 expression were significantly higher than that in specimens exhibiting low TXNDC5 expression (P<0.05)." (PMID 25663872, 2015).
tumor (continued). "TXNDC5 is involved in reducing the efficiency of photothermal therapy, a minimally invasive and highly specific antineoplastic treatment, by resisting oxidative stress damage and promoting tumor growth and metastasis." (PMID 38666927, 2024). "It is debatable whether the tumorigenic properties of TXNDC5 expression in RCC cells are related to the inhibitory regulation of lipocalin tumor suppressor signaling." (PMID 38629066, 2024). "Finally, TXNDC5 is a potential tumor-specific antigen for developing mRNA vaccines and an approach in designing a multi-epitope vaccine targeting TXNDC5 can potentially contribute to NSCLC." (PMID 38666927, 2024). "The study suggested that TXNDC5 is a key point in the pathway of HERG1 promotes tumor progression." (PMID 38629066, 2024). "TXNDC5 has been attributed to both oncogenic and tumor-suppressive features." (PMID 38666927, 2024). "Our data clearly demonstrated that TXNDC5 was enriched in the tumor area of hyperplastic blood vessels and microvascular proliferation which are known to contain highly proliferative cells and play a crucial role in tumor progression." (PMID 36106447, 2022). "The inactivation or downregulation of nuclear receptor 4A1 (NR4A1) downregulates TXNDC5, isocitrate dehydrogenase 1, and the mTOR (mammalian target of rapamycin) pathway, further promoting ROS generation, inducing apoptosis, and inhibiting tumor growth." (PMID 33228209, 2020). "Among the TXNDCs, TXNDC5 can have a role in both tumor progression and tumor suppression." (PMID 33228209, 2020). "Previous studies have shown that both HERG1 and TXNDC5 are involved in tumor cell proliferation, invasion, and angiogenesis, and may be useful in predicting the outcomes of certain tumor patients." (PMID 31331361, 2019). "Specifically, TXNDC5 promotes tumor cell differentiation, invasion, and angiogenesis, and its expression is positively correlated with poor survival of patients with certain tumor types." (PMID 31331361, 2019). "In addition, studies on TXNDC5, another member of the thioredoxin family, have revealed that it played a vital role in the proliferation and migration of tumor cells, acting as a tumor-enhancing gene." (PMID 30382079, 2018). "Numerous mesenchymal cells within the tumor tissue also exhibited significant TXNDC5 expression." (PMID 29207620, 2017). "TXNDC5 immunoreactivity in adjacent normal cervical tissues was observed in a few squamous epithelial cells and some mesenchymal cells, but the density of the positive staining was relatively reduced compared with tumor tissues." (PMID 29207620, 2017). "The upregulated expression of TXNDC5 may correlate with poorly-differentiated adenocarcinoma, lymph node metastasis and deeper tumor invasion." (PMID 25663872, 2015). "In these tumor processes, the interaction between the N-terminal region of TXNDC5 (amino acids 33 to 77) and Adipo-R1 (amino acids 1–70), which is induced by hypoxia, could play an important role as well." (PMID 25526565, 2014). "However, early in carcinogenesis, TXNDC5 may be downregulated due to a protective anticancer role, whereas later in tumor progression it is often upregulated." (PMID 38666927, 2024). "TXNDC5 gene weakens the PTT efficacy through protein processing in the endoplasmic reticulum signaling pathway; as a result, Cas9/sgRNA RNP knocked down the TXNDC5 gene, amplifying the photothermal hyperthermia effect against tumor." (PMID 35918694, 2022). "TXNDC5, as a protein induced by lack of oxygen, may be involved in these processes, acting as a tumor enhancer." (PMID 25526565, 2014). "In addition, DIM-C-pPhOH (30 mg/kg/d) also decreased expression of TXNDC5 and IDH-1 and induced CHOP expression in tumors from athymic nude mouse xenografts, demonstrating that C-DIM/NR4A1 antagonists-dependent inhibition of RCC cell and tumor growth is due, in part, to induction of stress." (PMID 26035713, 2015).
adenocarcinoma (2 papers, 2015 to 2024). A common cancer characterized by the presence of malignant glandular cells. "In the adenocarcinoma specimens exhibiting high TXNDC5 expression, the proportion of poorly-differentiated adenocarcinomas was significantly higher than that in specimens exhibiting low TXNDC5 expression (P<0.05)." (PMID 25663872, 2015). "Furthermore, the proportion of poorly-differentiated adenocarcinomas was significantly higher in the specimens with high TXNDC5 expression compared with the specimens exhibiting low TXNDC5 expression (P<0.05)." (PMID 25663872, 2015).
cardiovascular diseases (1 paper, 2024). "Further investigation into the regulatory mechanisms of TXNDC5 within the vascular pathways may lead to the development of targeted therapies for preventing or treating cardiovascular diseases." (PMID 38666927, 2024).
infection (1 paper, 2012). The state of being infected such as from the introduction of a foreign agent such as serum, vaccine, antigenic substance or organism. "The expression of PRDX4, SEC11C, ERlEC1 and TXNDC5 decreased in expression in B-lymphocytes after S. Enteritidis infection suggesting a suppression of common B-lymphocyte function and specialization of B-lymphocyte towards immunoglobulin expression after the infection." (PMID 23094107, 2012). "Prior to the infection, B-lymphocytes were the major producers of PRDX4, SEC11C, ERLEC1 and TXNDC5 and all immunoglobulins." (PMID 23094107, 2012).
TXNDC5 also shares sentences with these, for which no sentence is quoted: liver cancer (5 papers); neurodegenerative disease (3); brain cancer (2); colorectal adenoma (2); endothelial dysfunction (2); esophageal cancer (2); hyperglycaemia (2); aortic aneurysm (1); aortic atherosclerosis (1); atrial fibrillation (1); bladder cancer (1); brain diseases (1); carotid atherosclerosis (1); Cerebellar medulloblastoma (1); Cirrhosis (1); heart diseases (1); heart failure (1); idiopathic pulmonary fibrosis (1); leukemia (1); liver disease (1); lung adenocarcinoma (1); Lymph node (1); malaria (1); metastatic tumors (1); multiple myeloma (1); neuroblastoma (1); non-alcoholic fatty liver disease (1); Obesity (1); Parkinson disease (1); pulmonary arterial hypertension (1).
A further 7 diseases each share a sentence with TXNDC5 in 1 paper.